CLIC4 (CLIC family member 4)
Description:
In the soluble state, catalyzes glutaredoxin-like thiol disulfide exchange reactions with reduced glutathione as electron donor. Can insert into membranes and form voltage-dependent multi-ion conductive channels. Membrane insertion seems to be redox-regulated and may occur only under oxidizing conditions (By similarity). Has alternate cellular functions like a potential role in angiogenesis or in maintaining apical-basolateral membrane polarity during mitosis and cytokinesis. Could also promote endothelial cell proliferation and regulate endothelial morphogenesis (tubulogenesis). Promotes cell-surface expression of HRH3.
Synonyms: DKFZP566G223; CLIC4L; P64H1; H1; huH1; MTCLIC
Tractability: Antibody: UniProt places it where antibodies can reach, with high confidence; its Gene Ontology location is reachable by antibodies, with high confidence; UniProt predicts a signal peptide or a membrane-spanning region; the Human Protein Atlas places it where antibodies can reach. PROTAC: ubiquitination databases record sites on it; its protein half-life has been measured.
Target class: Enzyme; Oxidoreductase
Gene: Protein-coding gene on chromosome 1 (24,745,342 to 24,844,321, forward strand). Ensembl gene ENSG00000169504.
Subcellular location: Cytoplasm, cytoskeleton, microtubule organizing center, centrosome; Cytoplasmic vesicle membrane; Nucleus; Cell membrane; Mitochondrion; Cell junction; Endoplasmic reticulum membrane
Subcellular location (Human Protein Atlas): Centrosome; Plasma membrane; Calyx; Connecting piece; Principal piece
Gene Ontology:
Molecular function: protein binding; chloride channel activity
Biological process: cellular response to calcium ion; keratinocyte differentiation; negative regulation of cell migration; cell differentiation; chloride transport; establishment or maintenance of apical/basal cell polarity; regulation of cytoskeleton organization; chloride transmembrane transport
Cellular component: anchoring junction; apical part of cell; cell surface; cell-cell junction; centrosome; cytoplasm; cytosol; extracellular exosome; microtubule cytoskeleton; microvillus; midbody; mitochondrion; nuclear matrix; perinuclear region of cytoplasm; plasma membrane; actin cytoskeleton; endoplasmic reticulum membrane; membrane; cytoplasmic vesicle membrane; nucleus
Genetic constraint (gnomAD): Loss-of-function variants: 9 observed, 17.43 expected, observed/expected ratio (o/e) 0.52, 90% interval 0.31 to 0.9. The upper end of that interval is the gene's LOEUF score, 0.9, which puts it in group 3 of 6, group 1 being the genes least tolerant of losing a copy. Missense variants: 196 observed, 246.73 expected, observed/expected ratio (o/e) 0.79, 90% interval 0.71 to 0.89. Synonymous variants: 88 observed, 91.45 expected, observed/expected ratio (o/e) 0.96, 90% interval 0.81 to 1.15.
Homologues: Orthologues: chimpanzee CLIC4 (100% identical), macaque CLIC4 (99% identical), guinea pig CLIC4 (99% identical), mouse Clic4 (99% identical), pig CLIC4 (99% identical), rat Clic4 (98% identical), dog CLIC4 (98% identical), rabbit CLIC4 (92% identical), zebrafish clic4 (86% identical), tropical clawed frog clic4 (82% identical), Caenorhabditis elegans exl-1 (28% identical), Caenorhabditis elegans exc-4 (26% identical), and 29 more. Paralogues in human: CLIC6 (74% identical), CLIC5 (74% identical), CLIC1 (64% identical), CLIC2 (61% identical), CLIC3 (46% identical), EEF1G (21% identical), GSTT2 (20% identical), GSTT2B (20% identical), GSTT4 (19% identical), GDAP1 (18% identical), GDAP1L1 (18% identical), GSTO1 (18% identical), and 2 more.
Diseases named in the same sentence as CLIC4 in open-access papers:
CLIC4 is named in the same sentence as 72 diseases in open-access papers, as found by Europe PMC text mining. Sharing a sentence is not in itself a finding about the gene and the disease. The quoted sentences say what the papers report.
breast carcinoma (9 papers, 2005 to 2025). "These correlations, potentially skewed by the highly significant association with TNBC, suggested that higher CLIC4 expression in breast cancers was associated with more aggressive disease and poor outcome." (PMID 35727842, 2022). "Elevated CLIC4 predicted poor outcome in breast cancer patients and was linked to the TGF-β pathway." (PMID 35727842, 2022). "Downregulation of CLIC4 could promote tumor cell growth and clonogenicity in lung cancer and gastric cancer, while its upregulation could cause tumor cell growth in squamous cell carcinomas and breast cancer." (PMID 33014825, 2020). "These include a study on breast cancer cells, where CLIC4 was required to maintain mitochondrial function and resistance to exogenous oxidant assault." (PMID 41008519, 2025). "Breast cancer cells were injected into the 4th left mammary fat pad of Clic4 wildtype (WT) or KO female mice (day 0)." (PMID 35727842, 2022). "Further, in murine models of breast cancer, CLIC4 in the host microenvironment is required for lung metastasis." (PMID 35727842, 2022). "We show that elevated CLIC4 expression in human breast cancers predicts early invasion and poor outcome in women." (PMID 35727842, 2022). "A reduction in CCL5 at all Clic4 KO timepoints is particularly notable since CCL5 is reported to influence the development of breast cancer metastasis in human patients and experimental models." (PMID 35727842, 2022). "Experimentally, elevation of stromal CLIC4 is tightly linked to TGF-β signaling, a pathway causally associated with breast cancer progression and metastasis." (PMID 35727842, 2022). "Previous in situ studies have shown that elevation of CLIC4 in human cancers is particularly prominent in host stromal cells, consistent with our analysis of progressing breast cancer and cancers of the cervix, esophagus, and tongue." (PMID 35727842, 2022). "This unexpected result on metastatic competence was confirmed using an independent genetic model of C57BL/6-derived E0771 breast cancer cells injected into Clic4 WT, HET, and KO C57BL/6 female mice." (PMID 35727842, 2022). "Here, we used data available from the TCGA and METABRIC datasets to show that CLIC4 expression was higher in breast cancers from younger women and those with early-stage metastatic disease." (PMID 35727842, 2022). "Tumors evolving from xenografts of human breast cancer cells are substantially larger if co-transplanted with fibroblasts genetically altered to express high levels of CLIC4." (PMID 35727842, 2022). "Immunostaining of human breast and breast cancer tissue arrays revealed CLIC4 staining primarily in the acini and ducts of normal breast tissue that became more diffuse and intense, particularly in the stromal compartments of breast cancers." (PMID 35727842, 2022). "In this current study, we established a relationship between elevated CLIC4 expression in multiple breast cancer data sets and the progressive clinical course of human breast cancer." (PMID 35727842, 2022). "The TGF-β-regulated Chloride Intracellular Channel 4 (CLIC4) is an essential participant in the formation of breast cancer stroma." (PMID 35727842, 2022). "METABRIC data revealed that CLIC4 expression in breast cancers significantly increased in patients progressing from Stage 0 to Stage I and remained elevated compared to those with in situ lesions." (PMID 35727842, 2022). "CLIC4 expression is higher in breast cancers from young patients whose tumors are often more aggressive, in patients with triple negative breast cancer, those with local metastases and with poor prognosis by Kaplan-Meier analysis." (PMID 35727842, 2022). "Interstitial fluid, extracted through drains from mastectomy sites of patients with highly aggressive breast cancers, strongly induce CLIC4 in cultured human breast cancer cells relative to interstitial fluid from mastectomy patients with low grade lesions." (PMID 35727842, 2022).
breast carcinoma (continued). "This suggested that the elevation of CLIC4 had significant prognostic implications mainly within 10 years after the diagnosis for breast cancer patients." (PMID 35727842, 2022). "Recently, CLIC4 has become a molecule of interest in breast cancer, where it is expressed in stromal cells." (PMID 35727842, 2022). "CLIC4 was also shown to be upregulated in stromal cells of breast cancer patients as a response to TGF-β treatment." (PMID 32116799, 2020). "Because growing evidence has indicated that CLIC4 is involved in the development of different cancers, including cutaneous cancer, breast cancer, ovarian cancer and others, we also investigated CLIC4 expression in surgical specimens from HNSCC patients." (PMID 26816615, 2016). "To assess whether CLIC4 expression in tumor tissue correlated with any clinical data in breast cancer patients, we analyzed data from the Molecular Taxonomy of Breast Cancer International Consortium (METABRIC) study and The Cancer Genome Atlas (TCGA) database." (PMID 35727842, 2022). "Altogether, CLIC4 expression in human breast cancers may serve as a prognostic biomarker; therapeutic targeting of CLIC4 could reduce primary tumor viability and host metastatic competence." (PMID 35727842, 2022). "We discovered that host CLIC4 is required for breast cancer metastasis and identified CLIC4 functions that may contribute to metastatic competence." (PMID 35727842, 2022). "Therefore, we turned to animal models to address the contribution of CLIC4 in the development of primary and metastatic breast cancer." (PMID 35727842, 2022). "In addition, there was upregulated expression of two genes that have previously been shown to be highly associated with tumor-associated fibroblasts in breast cancer (CXCL12 and CLIC4) and upregulation of the COX2 gene." (PMID 15987422, 2005). "Similarly, CLIC1 and CLIC4 were shown to regulate mitochondrial structure and biogenesis, and another study found CLIC4 was required to regulate redox homeostasis and mitochondrial function in breast cancer cells." (PMID 41008519, 2025). "However, these associations did not reveal the underlying biological contribution of CLIC4 to breast cancer progression." (PMID 35727842, 2022). "We now provide human proteomic data indicating that CLIC4 expression levels and those of members of the TGF-β pathway in breast cancer patients are highly correlated implying that CLIC4 levels could serve as a surrogate TGF-β effector of TGF-β-driven pathologies." (PMID 35727842, 2022). "Therefore, we genetically manipulated Clic4 in the host or the tumor cells in syngeneic immunocompetent murine breast cancer models with reproducible lung metastases to clarify whether CLIC4 in the host and/or in the tumor cells is required for the development and progression of breast cancer." (PMID 35727842, 2022). "CLIC4 expression is highly responsive to TGF-β in primary human mammary fibroblasts, and human breast cancer cells release TGF-β that induces the conversion of fibroblasts to myofibroblasts through a CLIC4-dependent pathway." (PMID 35727842, 2022). "Microarray studies have identified changes in CLIC5 and CLIC6 expression in breast cancer tissues along with CLIC1 and CLIC4." (PMID 32116799, 2020). "Constitutive ablation of host Clic4 in two murine metastatic breast cancer models nearly eliminated lung metastases without reducing primary tumor weight, while tumor cells ablated of Clic4 retained metastatic capability in wildtype hosts." (PMID 35727842, 2022). "The role of CLIC4 in tumor stroma was initially identified by Ronnov-Jessen and colleagues, who observed that TGF-β exposure significantly upregulated CLIC4 expression in the myofibroblast stroma of breast cancer, suggesting its involvement in stromal remodeling during cancer progression." (PMID 39595145, 2024).
ovarian carcinoma (8 papers, 2016 to 2024). A malignant neoplasm originating from the surface ovarian epithelium. "Knockdown of either CLIC4 or CLIC1 resulted in slower growth of ovarian cancer cells suggesting a role of CLICs in cell proliferation and cell migration." (PMID 35223789, 2022). "Compared with normal and benign controls, the level of CLIC4 protein was significantly increased in serum from ovarian cancer patients." (PMID 34440131, 2021). "Recently, CLIC4 has been found to have broad prospects as a serum/tissue biomarker and therapeutic target for epithelial ovarian cancer." (PMID 34440131, 2021). "Expression levels of CLIC1 and CLIC4 have also been implicated in patient survival, with elevated CLIC4 expression a negative indicator of patient survival in ovarian cancer." (PMID 35223789, 2022). "Elevated CLIC4 levels in plasma of several human diseases, including progression of ovarian cancer and the pathogenesis of pulmonary hypertension, suggest the protein may have systemic as well as local cellular effects." (PMID 35727842, 2022). "CLIC4 is shown to exhibit varied expression and activity in several tumor types including ovarian, colon, bladder cancers, glioma, melanoma and even present in the exosomes ejected from human ovarian cancer cell lines." (PMID 32116799, 2020). "CLIC4 follows the same pattern as CLIC3 and our analysis is in agreement with an earlier report on ovarian cancer." (PMID 32116799, 2020). "Along with CLIC4, CLIC1 is a promising biomarker for epithelial ovarian cancer where its expression predicts patient survival." (PMID 32116799, 2020). "In ovarian cancer, CLIC1 has been identified as a promising biomarker with prognostic value, impacting patient survival and possibly serving in conjunction with CLIC4." (PMID 38027011, 2023). "Studies have shown two members of the CLIC protein family, CLIC1 and CLIC4, to be significantly upregulated in EOC patients compared to healthy controls, and shed into the blood of ovarian cancer patients." (PMID 35223789, 2022).
lung carcinoma (7 papers, 2014 to 2025). "A proteomic study in lung cancer revealed that the down-regulation of CLIC4 is associated with carcinogenesis in some types of lung cancer." (PMID 37408210, 2023). "Among them, CLIC1, CLIC3, and CLIC4 have been investigated more extensively, particularly in the context of lung cancer, inflammatory diseases, and pulmonary arterial hypertension." (PMID 41907764, 2025). "CLIC4 restoration in lung cancer cell lines attenuates cell proliferation, suggesting CLIC4 as a tumor suppressor." (PMID 37408210, 2023). "In this regard, we first studied the relative mRNA expression level of CLIC4 in different lung cancer cell lines and normal lung fibroblast cell line, MRC-5." (PMID 34440131, 2021). "Previous studies demonstrated that CLIC4 protein levels were reduced in neoplastic cells in several types of human malignancies including lung cancer." (PMID 24503901, 2014). "The restoration of CLIC4 in lung cancer cell lines in which CLIC4 expression was reduced attenuated their growth activity." (PMID 24503901, 2014). "To verify the potential involvement of CLIC4 in carcinogenesis in the lung, we here examined lung cancer cell lines and primary human lung cancers for the expression of CLIC4, and analyzed the correlation between its expression levels and different clinicopathologic parameters." (PMID 24503901, 2014). "The knockdown of CLIC4 in an immortalized non-cancerous cell line elevated growth activity, and the restoration of CLIC4 in lung cancer cell lines in which CLIC4 expression was reduced attenuated their growth activity, suggesting that CILC4 could be a tumor suppressor." (PMID 24503901, 2014). "The immunohistochemical expression of the CLIC4 protein was weaker in primary lung cancer cells than in non-tumorous airway epithelial cells and was occasionally undetectable in some tumors." (PMID 24503901, 2014). "Among the lung cancer cell lines examined, some cell lines (A549, TKB14, and H2087) had lower CLIC4 protein levels than those in immortalized non-cancerous airway cells." (PMID 24503901, 2014).
pulmonary arterial hypertension (7 papers, 2016 to 2026). Pulmonary arterial hypertension (PAH) is a group of diseases characterized by mean pulmonary artery pressure >20 mmHg and elevated pulmonary arterial resistance leading to right heart failure. "Although we have not explored the role of CLIC4 in endothelial cells in the context of SSc in this study, it is interesting that aberrant expression of CLIC4 has previously been implicated in Pulmonary arterial hypertension (PAH) which hints at a role for CLIC4 in SSc endothelial cell dysfunction." (PMID 40890810, 2025). "In pulmonary arterial hypertension, CLIC4 gene deletion markedly attenuated the development of chronic hypoxia-induced pulmonary hypertension in mice, indicating that CLIC4 is a mediator of endothelial dysfunction in pulmonary hypertension." (PMID 28860555, 2017). "CLIC4, a gene that encodes the chloride intracellular channel protein 4, regulates vasculogenesis through endothelial tube formation; abnormal CLIC4 expression may play a role in pulmonary arterial hypertension pathology." (PMID 27467526, 2016).